NHEG1 (neuroblastoma highly expressed DDX5 stabilizing lncRNA 1)
Gene: Long non-coding RNA gene on chromosome 6 (136,982,165 to 136,993,234, reverse strand). Ensembl gene ENSG00000225391.
Diseases named in the same sentence as NHEG1 in open-access papers:
NHEG1 is named in the same sentence as 5 diseases in open-access papers, as found by Europe PMC text mining. Sharing a sentence is not in itself a finding about the gene and the disease. The quoted sentences say what the papers report.
neuroblastoma (6 papers, 2021 to 2024). Neuroblastoma (NB) is the most common solid, extracranial childhood tumor. "In our study, we explored the functional roles of lncRNA NHEG1 in neuroblastoma and the underlying molecular mechanism." (PMID 34889712, 2021). "The upregulation of NHEG1, a nuclear lncRNA, has been shown to promote neuroblastoma cell aggressiveness, resulting in unfavorable OS and EFS." (PMID 38891878, 2024). "LncRNA neuroblastoma highly expressed 1 (NHEG1) increased high mobility group box 1 (HMGB1) expression by sponging miR-655 to promote neuroblastoma progression." (PMID 35030969, 2022). "NHEG1 inhibits the degradation of DDX5 through the ubiquitin–proteasome pathway to promote neuroblastoma progression." (PMID 35992805, 2022). "The upregulation of lncRNA NHEG1 and downregulation of miR-665 have been also reported in neuroblastoma." (PMID 34889712, 2021). "In fact, in NB, long non-coding RNA (lncRNA) neuroblastoma highly expressed 1 (NHEG1) negatively regulates the activity of miR-665, which cannot inhibit high mobility group box 1 (HMGB1) expression, causing the aggressive phenotype of neuroblastoma cells." (PMID 39202438, 2024). "LncRNA NHEG1 could sponge miR-665 which inhibits HMGB1 that promotes neuroblastoma, so neuroblastoma tumor progression is upregulated by the lncRNA NHEG1." (PMID 37894282, 2023). "Recent research has shown that NHEG1 additionally mediates oncogenic effects by acting as a ceRNA of miR-665, a regulator of HMGB1, a protein that promotes stemness in neuroblastoma." (PMID 38891878, 2024). "The siRNA-mediated downregulation of NHEG1 or DDX5 in murine xenograft models led to the differentiation and reduced growth and aggressiveness of neuroblastoma cells." (PMID 38891878, 2024). "LncRNA NHEG1 has multiple MREs for miR-665 and can thus inhibit HMGB1, thereby suppressing neuroblastoma cell proliferation, migration, and invasion." (PMID 37894282, 2023). "Long non-coding (lncRNA) neuroblastoma highly expressed 1 (NHEG1) has been reorganized as a prognostic factor in neuroblastoma (NB), but the molecular mechanisms in the suppression of neuroblastoma remain to be elucidated." (PMID 34889712, 2021). "Our study indicates that lncRNA NHEG1/miR-665/HMGB1 axis may play an important role in regulating the aggressiveness and the progression of neuroblastoma." (PMID 34889712, 2021). "Together, our data demonstrated that lncRNA NHEG1 serves as a competitive partner to negatively regulate the activity of miR-665, which relieves the inhibition on HMGB1 expression and promotes the aggressive phenotype of neuroblastoma cells." (PMID 34889712, 2021). "Our study suggests that lncRNA NHEG1/miR-665/HMGB1 axis may play an important role in regulating the aggressiveness and progression of neuroblastoma." (PMID 34889712, 2021).
lung adenocarcinoma (1 paper, 2021). A carcinoma that arises from the lung and is characterized by the presence of malignant glandular epithelial cells. "A previous study suggests that lncRNA NHEG1 regulates a network of microRNAs in human lung adenocarcinoma, implying the involvement of miRNAs in the regulatory network by lncRNA NHEG1." (PMID 34889712, 2021). "As an example, lncRNA neuroblastoma highly expressed 1 (NHEG1) was a lncRNA which is predicted to regulate a network of microRNAs in human lung adenocarcinoma." (PMID 34889712, 2021).
tumor (2 papers, 2021 to 2023). "Pearson correlation analysis further revealed a significant negative correlation between the expression levels of miR-665 and lncRNA NHEG1 in the NB tumor samples." (PMID 34889712, 2021). "In order to investigate the expression level of lncRNA NHEG1 in NB, tumor samples and adjacent normal tissues were collected from 60 NB patients." (PMID 34889712, 2021). "In this study, we first collected NB tumor samples and adjacent normal tissues to compare lncRNA NHEG1 expression." (PMID 34889712, 2021). "Consistently, we showed that lncRNA NHEG1 may factor the progression of NB since it is upregulated in NB tumor and cell lines." (PMID 34889712, 2021). "We collected NB tumor samples and adjacent normal tissues to compare lncRNA NHEG1 expression." (PMID 34889712, 2021). "We observed that lncRNA NHEG1 was significantly upregulated in NB tumor and cell lines." (PMID 34889712, 2021). "Furthermore, there was a negative correlation between the expression levels of miR-665 and HMGB1, and a positive correlation between the expression levels of lncRNA NHEG1 and HMGB1 in NB tumor sample." (PMID 34889712, 2021).
NHEG1 also shares sentences with these, for which no sentence is quoted: Obesity (1 paper); retinoblastoma (1).